PRCC (proline rich mitotic checkpoint control factor)
Diseases named in the same sentence as PRCC in open-access papers (continued):
Sharing a sentence is not in itself a finding about the gene and the disease.
tumor (continued). "As the introduction of immune checkpoint blockade (ICB) into the treatment of RCC has transformed the therapeutic landscape in this recalcitrant disease, tumour microenvironments (TME) variation of pRCC may influence ICB response." (PMID 35037540, 2022). "Furthermore, increased RP11-63A11.1 inhibited the proliferation and induced apoptosis of pRCC cells, indicating RP11-63A11.1 served as a tumor suppressor in pRCC." (PMID 34663322, 2021). "Furthermore, PLK1 is a component gene of Overlap66; PLK1 inhibitor significantly reduced OIP5-promoted pRCC cell proliferation in vitro and tumor growth in vivo." (PMID 34503297, 2021). "For pRCC we only detect low amounts of overall Perl’s staining, with localized positive staining mostly in tumor cells, whereas we observed high amounts of iron deposits in chRCC, mostly within the tumor stroma." (PMID 32106629, 2020). "Diffuse, strong AMACR expression is typical of PRCC (70-100%); however, reactivity has also been observed to a variable extent in 4-68% of CCRCC, sometimes less diffusely or associated with higher-grade tumor components." (PMID 24568263, 2014). "Notably, pRCC is structurally and functionally closer to renal tubules, the mammalian counterpart of fly MTs, which allows our fly model to provide relevant mechanistic insight to this tumor subtype." (PMID 40832336, 2025). "Reducing MIR503HG expression in pRCC could partially reverse the negative effect of tumor-induced lymph-vessel formation caused by Everolimus." (PMID 37416763, 2023). "We may investigate the genetic differences of PRCC using tissue microarray, which has been widely utilized to find possible diagnosis and therapy targets in tumor growth and has also been shown to be a valuable way for identifying novel biomarkers in other illnesses." (PMID 35655917, 2022). "Thus, inhibiting Yes and the subsequent transcriptional activity of YAP1 had a substantial anti-tumor cell effect both in vitro and in vivo and may provide a viable therapeutic approach for patients with NF2-deficient PRCC." (PMID 29535838, 2018). "The DEG and GSEA results suggest that tumor metabolism and the KRAS signaling pathway are different between PRNRP and KRAS-mutant PRCC." (PMID 41375035, 2025). "Five tumor antigens, including ALOX15B, HS3ST2, PIGR, ZMYND15 and LIMK1, were identified for PRCC, which were correlated with patients’ prognoses and infiltration levels of APCs." (PMID 36836593, 2023). "Through proteomics and bioinformatics analyses of PRCC, we found that high‐mobility group protein A2 (HMGA2) was highly expressed in tumor tissues, and patients with high HMGA2 expression exhibited shorter survival times." (PMID 37283291, 2023). "Clinical decisions should be based on the different molecular subtypes of pRCC; therefore, sensitivity to the 30 common anti-tumour drugs was compared between the high– and low–SHMT2 expression groups to determine potential treatment modalities for pRCC." (PMID 36110969, 2022). "Both tumour locations showed a similar staining pattern in CCRCC (Chi-square test, p = 0.6), PRCC (p= 0.64), ChRCC (p = 0.3) and RO (p = 0.31)." (PMID 33578778, 2021). "The interaction of PRCC and its TME affected the whole process from tumor occurrence and progress to metastasis and recurrence, which created plenty of opportunities for diagnosis, treatment and prognosis of PRCC patients." (PMID 33993869, 2021). "Among six SFs, the level of SF3B4 in ACC cases with the tumor stage III and the level of PRCC and SF3B4 in ACC cases with stage IV were statistically different from those in stage I, which is consistent with the results from the GEPIA database." (PMID 33101358, 2020).
tumor (continued). "Prior work has shown that a subset of pRCC, primarily Type 2 pRCC, is enriched for gene signatures of MYC activation and that tumours with MYC activation have a worse overall survival." (PMID 28593993, 2017). "Taken together, five tumor antigens (ALOX15B, HS3ST2, PIGR, ZMYND15, and LIMK1), with potentially provocative effects on immunological functions, were identified and considered as eligible candidates for anti-PRCC mRNA vaccine development." (PMID 36836593, 2023). "For negative cases, such as ccRCC and pRCC, 2F and 1G1R signal patterns were observed in 1% and 22–88.35% of male tumor cells, respectively." (PMID 33004995, 2020). "PEAR1 interactions with HDGF and PRCC might modulate their cancer-related role and open up for future research of PEAR1 in the tumour biology field." (PMID 29614055, 2018). "Our data requires validation and further elucidation in pre-clinical models, but these results may predict an increased immune response to the tumor in black patients and also an increased response to immunotherapies and or VEGFR inhibitors for black patients with advanced pRCC." (PMID 28029648, 2017). "The role of c-met in pRCC has not been clearly elucidated but in hereditary pRCC it is suggested that germline mutations of the MET gene promote proliferation, tubulogenesis, and tumour initiation." (PMID 26448938, 2015). "Tumor cells from all CCRCC, PRCC, ChRCC and RO were negative." (PMID 28809959, 2017).
cancer (30 papers, 2013 to 2025). A tumor composed of atypical neoplastic, often pleomorphic cells that invade other tissues. "PRCC also displays mutations in previously studied cancer-related pathways; these include NF2 (Hippo pathway), SMARCB1 and PBRM1 (SWI/SNF complex), and chromatin modifier pathways (SETD2, KDM6A, and BAP1)." (PMID 38162463, 2023). "In contrast to ccRCC18, relatively little is known about the mutations that drive pRCC growth and the clonality of copy number events and single-nucleotide variants (SNVs), apart from the small minority of cancers with changes in MET and FH." (PMID 25790038, 2015). "We initially investigated all 31 cancers and paired constitutional DNA for mutations in the Mendelian pRCC genes MET, FH and FLCN." (PMID 25790038, 2015). "Genome and exome sequencing have shown that pRCC driver mutations overlap with those of other cancers, but there are also genetic features specific to pRCC." (PMID 25790038, 2015). "Chromatin remodeling genes are frequently mutated in pRCC and many other cancers, including ccRCC." (PMID 28358873, 2017). "These included pRCC (malignant neoplasm), oncocytoma (benign neoplasm), PRNRP, and eosinophilic variant of ccRCC (malignant neoplasm)." (PMID 40860802, 2025). "This sets PRCC apart from many other cancers, such as lung, bladder, colon, rectal, and thyroid carcinomas and adenocarcinomas, where BTLA tends to be downregulated and expressed at lower levels in cancer cells compared to their healthy counterparts." (PMID 39796121, 2024). "LncRNAs, together with miRNAs and mRNAs, form intricate gene expression regulatory networks that play a crucial role in the occurrence, development, and regulation of cancers, including pRCC." (PMID 35626699, 2022). "The high ectopic expression of PRCC not only causes HCC cells to resist to cell death induced by DNA damage, but also causes cancer cells with numerous DNA mutations to become increasingly heterogeneous, finally leading to a poor prognosis for HCC patients." (PMID 34715922, 2021). "The high ectopic expression of PRCC not only caused HCC cells to resist to cell death induced by DNA damage, but also endowed cancer cells with numerous DNA mutations to become increasingly heterogeneous, finally leading to a poor prognosis in HCC patients." (PMID 34715922, 2021). "PRCC expression profiles and clinical data were extracted from The Cancer Gene Atlas (TCGA) and Gene Expression Omnibus (GEO) database." (PMID 33993869, 2021). "The high ectopic expression of PRCC made cancer cells insensitive to DNA damage, and enhanced the heterogeneity of HCC cells by inhibiting the JNK/ATM/ATR/ATF2 axis." (PMID 34715922, 2021). "In recent years, with the development of molecular biology technology and bioinformatics, new biomarkers have the potential to be used as prognostic factors for different types of cancer, including pRCC." (PMID 32536823, 2020). "The mRNASeq data of PRCC and adjacent normal tissue in The Cancer Genome Atlas was analyzed to identify 1148 differentially expressed genes, on which weighted gene co-expression network analysis was performed." (PMID 28427189, 2017). "In this study, we combined the analysis of five PRCC gene expression datasets derived from Gene Expression Omnibus (GEO) and The Cancer Genome Atlas (TCGA) by using integrative bioinformatics pipelines." (PMID 27705936, 2016). "The Cancer Genome Atlas database was analyzed to find targets for ccRCC, pRCC, and chRCC." (PMID 36808829, 2023). "In the PRCC overexpression group, the ability of cancer cells to form spheroids was inhibited." (PMID 34715922, 2021). "RP11-63A11.1 functioned as a cancer suppressor in pRCC and it might be a potential therapeutic target for treating pRCC." (PMID 34663322, 2021). "The next important question was to determine if some phenotypic cancer marker known to be expressed in human PRCC could be found in met-IPSC-derived structures." (PMID 31575031, 2019).
cancer (continued). "Of all cancer forms analyzed, CCRCC and PRCC displayed the highest expression levels for ACE2 and NRP1 mRNA, whereas again TMPRSS2 expression was lower but not negligible." (PMID 36595529, 2023). "The expressional levels for ACE2 and NRP1 mRNA occupy first and second position across all cancers analysed for CCRCC and PRCC, whereas TMPRSS2 was more modestly expressed." (PMID 36595529, 2023). "Finally, ranking cancer driver mutations by their correlation with glutamine reveals that KRAS and ERBB4 have the strongest negative correlation (indicating that mutation is associated with a reduction of glutamine), and PRCC, JUN and PIK3CA mutations rank highly with an accumulation of glutamine." (PMID 36321551, 2022). "Significant differences were found between quite a few cancer tissues and their normal counterparts, including BLCA, BRCA, CHOL, COAD, HNSC, chRCC, ccRCC, pRCC, LIHC, LUAD, LUSC, READ, THCA, STAD, UCEC." (PMID 34193180, 2021). "Some previous studies have explored the relationships between methylation-driven genes and the prognosis of certain cancers, such as esophageal squamous cell carcinoma, lung adenocarcinoma, and bladder cancer, but currently, there is no such report for pRCC." (PMID 32536823, 2020). "Among the 5 mRNAs which are associated with the prognosis of pRCC, some have been reported to express in cancer or other diseases, but have not been examined in pRCC." (PMID 30822312, 2019). "While integrin-associated protein complexes mediate tumorigenesis and metastases in many types of cancers it is not known whether integrin-mediated signaling impacts PRCC and differs between PRCC1 and PRCC2." (PMID 27705936, 2016). "A recent clinical study suggested that cancer-specific survival differed significantly between adult patients with positive TFE3 rearrangement RCCs and adult patients with negative TFE3 rearrangement PRCC, which implied that adult RCCs with TFE3 rearrangement may be a clinically aggressive tumour." (PMID 32042048, 2020).
benign neoplasm (2 papers, 2013 to 2025). A neoplasm which is characterized by the absence of morphologic features associated with malignancy (severe cytologic atypia, tumor cell necrosis, and high mitotic rate). "In addition to PRCC, these genes also play a role in other diseases such as artery, vascular, cardiovascular system, urinary system, kidney, and benign neoplasm." (PMID 40051609, 2025).
PRCC also shares sentences with these, for which no sentence is quoted: syphilis (4 papers); clear cell renal cell carcinoma (2); gastric cancer (2); infection (2); ovarian carcinoma (2); bladder carcinoma (1); cardiac diseases (1); CNS tumors (1); collecting duct carcinoma (1); glioma (1); hereditary cancer (1); leukemia (1); liver fibrosis (1); lumbago (1); lung adenocarcinoma (1); lymphoma (1); microphthalmia (1); oral squamous cell carcinoma (1); pancreatic cancer (1); perivascular epithelioid cell neoplasms (1); prostate carcinoma (1); sarcoma (1); triple-negative breast carcinoma (1); urothelial carcinoma of (1).